MCM3 (minichromosome maintenance complex component 3)
Diseases named in the same sentence as MCM3 in open-access papers (continued):
Sharing a sentence is not in itself a finding about the gene and the disease.
colon cancer (5 papers, 2013 to 2022). "To further verify protein expression, we collected paired colon tumors and NATs and obtained that two of 42-tumor-associated RLBPs, MCM3, and MCM5, exhibited very high expression in tumors compared to the NATs." (PMID 36428700, 2022).
cervical squamous cell carcinoma (4 papers, 2013 to 2021). A squamous cell carcinoma arising from the cervical epithelium. "MCM4 along with MCM3 has been reported to be highly expressed in cervical squamous cell carcinoma by immunochemistry." (PMID 30150654, 2018).
esophageal cancer (4 papers, 2018 to 2025). A primary or metastatic malignant neoplasm involving the esophagus. "On further validation, MCM3 was finally selected and its expression in esophageal cancer was analyzed in TCGA database which showed high expression in esophageal cancer tissues compared to normal tissues." (PMID 38200573, 2024). "The results showed that MCM3 was significantly overexpressed in cholangiocarcinoma (CHOL), Colon adenocarcinoma (COAD), esophageal carcinoma (ESCA), LIHC, Lung adenocarcinoma (LUAD), lung squamous cell carcinoma (LUSC), rectum adenocarcinoma (READ), stomach adenocarcinoma (STAD) and other cancers." (PMID 39991578, 2025).
lymphoma (4 papers, 2010 to 2022). A malignant (clonal) proliferation of B- lymphocytes or T- lymphocytes which involves the lymph nodes, bone marrow and/or extranodal sites. "MCM3 for example, has been identified being overexpressed in several cancers including leukemia and lymphoma." (PMID 36230614, 2022). "When cohorts of Mcm3+/− and Mcm3+/Lox mice were established for longevity studies, both groups presented a slight but significant reduction in lifespan and an increased incidence of tumors, mainly lymphomas originated in the mesenteric lymph nodes that in multiple cases infiltrated to other organs." (PMID 26456157, 2015). "However, although Mcm3 hemizygosity rescued viability of Mcm4Chaos3/Gt mice, these animals were cancer prone with a shorter latency (by ∼6 months) and different spectrum (primarily lymphomas) than Mcm4Chaos3 homozygotes." (PMID 20838603, 2010).
osteosarcoma (4 papers, 2017 to 2024). A usually aggressive malignant bone-forming mesenchymal neoplasm, predominantly affecting adolescents and young adults. "In the present study, the co-immunoprecipitation technique was used to explore the underlying mechanism by which MCM2 and MCM3 influence osteosarcoma." (PMID 28460433, 2017). "Further validation showed that high MCM2 and MCM3 expression levels in osteosarcoma were associated with a poor prognosis." (PMID 28460433, 2017). "To date, the role and underlying mechanism of MCM2 and MCM3 involved in osteosarcoma remain largely unclear." (PMID 28460433, 2017). "In order to determine the underlying mechanism by which MCM2 and MCM3 promote osteosarcoma, co-immunoprecipitation was performed in 293T cells." (PMID 28460433, 2017). "(2017) identified proteins minichromosome maintenance protein 2 (MCM2) and minichromosome maintenance protein 3 (MCM3) through MS analysis of osteosarcoma cell lines and demonstrated an association of positive IHC expression with inferior tumor free- and overall- survival in 129 tissue samples." (PMID 37197427, 2023). "In sum, we hypothesized that MCM2 and MCM3 were associated with the proliferation of osteosarcoma cells." (PMID 28460433, 2017). "Thus, MCM2 and MCM3 are associated with DHX9 in osteosarcoma cells." (PMID 28460433, 2017). "IF of tumour cells from the HPA database showed that MCM3 protein was localized in the nuclei of U2OS (osteosarcoma) and A-431 (cutaneous squamous cell) cell lines." (PMID 38698811, 2024). "Functional screening was conducted on nine chosen proteins and inhibition of proteins MCM2 and MCM3 were found to reduce osteosarcoma cell proliferation." (PMID 37197427, 2023). "Collectively, knockdown of MCM2 or MCM3 dramatically inhibits osteosarcoma cell growth in vitro and in vivo." (PMID 28460433, 2017). "To further determine the clinicopathological significance of MCM2 and MCM3 in osteosarcoma, we performed an immunohistochemical (IHC) analysis of MCM2 and MCM3 using a tissue microarray that included an independent set of 129 cases of osteosarcoma." (PMID 28460433, 2017). "By functional screening, minichromosome maintenance protein 2 (MCM2) and minichromosome maintenance protein 3 (MCM3) were found to be related to osteosarcoma cell growth." (PMID 28460433, 2017). "The data revealed that the knockdown of MCM2 or MCM3 significantly inhibited the growth of osteosarcoma cells." (PMID 28460433, 2017). "Since MMC2 and MCM3 interact with DHX9 in osteosarcoma cells, it is plausible that they function via DHX9, and DHX9 plays an important role in osteosarcoma cell proliferation." (PMID 28460433, 2017). "This study, for the first time, demonstrates the interactions of MCM2/MCM3 with DHX9 in osteosarcoma cells." (PMID 28460433, 2017). "Taken together, MCM2 and MCM3 were correlated with DHX9 in tumor samples and were associated with poor prognosis in osteosarcoma patients." (PMID 28460433, 2017). "A rescue study showed that the decreased growth of osteosarcoma cells by MCM2 or MCM3 knockdown was reversed by DHX9 overexpression, indicating that MCM2 and MCM3 activity was DHX9-dependent." (PMID 28460433, 2017). "To assess interactions between proteins, we pulled down MCM2 or MCM3 and probed their interactions with other proteins in 293T cells and osteosarcoma cells." (PMID 28460433, 2017). "The results of this study demonstrated that knockdown of MCM2 or MCM3 inhibited osteosarcoma cell growth in vitro and in vivo." (PMID 28460433, 2017). "The overexpression of DHX9 rescued the MCM2 and MCM3 knockdown-induced osteosarcoma growth inhibition, showing that the control of cell proliferation by MCM2 and MCM3 was largely dependent on DHX9." (PMID 28460433, 2017). "In co-immunoprecipitation and co-localization experiments, MCM2 and MCM3 were found to interact with DExH-box helicase 9 (DHX9) in osteosarcoma cells." (PMID 28460433, 2017).
osteosarcoma (continued). "Taken together, MCM2 and MCM3 promote osteosarcoma progression via associations with DHX9 and thus are potential therapeutic targets for patients with osteosarcoma." (PMID 28460433, 2017). "Overexpression of DHX9 rescued the MCM2 and MCM3 knockdown-induced osteosarcoma growth inhibition by regulating numerous biological processes." (PMID 28460433, 2017). "Knockdown of MCM2 and MCM3 significantly inhibited osteosarcoma growth in vitro and in vitro." (PMID 37197427, 2023). "Here, we show that knockdown of MCM2 or MCM3 inhibits osteosarcoma growth in vitro and in vivo." (PMID 28460433, 2017). "However, the functions and molecular mechanisms of MCM2 and MCM3 in osteosarcoma are still far from fully understood." (PMID 28460433, 2017). "More importantly, this report provides, for the first time, experimental evidence for interactions of MCM2 and MCM3 with DHX9 in osteosarcoma cells and the importance of these interactions, clarifying the molecular mechanisms of MCM2 or MCM3-mediated tumorigenesis." (PMID 28460433, 2017). "Taken together, these results indicated that MCM2 or MCM3 knockdown could hinder the tumorigenesis of osteosarcoma cells in vivo." (PMID 28460433, 2017). "Our data demonstrated that knockdown of MCM2 or MCM3 inhibited osteosarcoma cell proliferation." (PMID 28460433, 2017). "Notably, MCM2 and MCM3 expression levels were positively correlated with the DHX9 expression level in tumor samples and were associated with a poor prognosis in patients with osteosarcoma." (PMID 28460433, 2017). "MCM2 and MCM3 may be sensitive biomarkers to predict prognosis for osteosarcoma patients." (PMID 28460433, 2017). "By functional screening, MCM2 and MCM3, components of the MCM2-7 complex, were found to be related to osteosarcoma proliferation." (PMID 28460433, 2017). "Further analysis indicated that MCM2 and MCM3 levels were positively correlated with recurrence (P = 0.000), indicating that MCM2 and MCM3 play important roles in osteosarcoma recurrence." (PMID 28460433, 2017). "A positive correlation between MCM2 or MCM3 and DHX9 expression was detected in osteosarcoma tissues." (PMID 28460433, 2017). "The results showed that knockdown of MCM2 or MCM3 inhibited osteosarcoma cell proliferation in MNNG/HOS cells, suggesting that they played important roles in the tumorigenesis of osteosarcoma." (PMID 28460433, 2017). "Collectively, these results reveal that knockdown of MCM2 or MCM3 inhibits osteosarcoma cell proliferation via DHX9 and DHX9 plays an oncogenic role in osteosarcoma." (PMID 28460433, 2017). "A Spearman correlation analysis revealed a significant correlation between the expression levels of MCM2 and DHX9 (R = 0.195, P = 0.027), as well as between the levels of MCM3 and DHX9 (R = 0.248, P = 0.005) in osteosarcoma tissues." (PMID 28460433, 2017). "Notably, we found that MCM2 and MCM3 were independent prognostic factors for tumor-free survival (TFS) and overall survival (OS) in patients with osteosarcoma." (PMID 28460433, 2017). "MCM2 and MCM3 were found to interact and co-localize with DHX9 in osteosarcoma." (PMID 28460433, 2017). "In addition, positive correlations between both MCM2 and MCM3 and DHX9 were found in osteosarcoma." (PMID 28460433, 2017). "However, the role of DHX9 in osteosarcoma and whether MCM2 and MCM3 function via DHX9 are largely unknown." (PMID 28460433, 2017).
renal cell carcinoma (4 papers, 2021 to 2025). "A previous study suggested that MCM3 phosphorylation is a new mechanism for regulating the proliferation and apoptosis of renal cell carcinoma cells." (PMID 38698811, 2024). "Gao showed that PLK1 affects cell proliferation and apoptosis by boosting MCM3 phosphorylation in renal cell carcinoma (RCC)." (PMID 34992654, 2021). "In addition, phosphorylated MCM3 has been shown to promote cell proliferation and inhibit cell apoptosis in renal cell carcinoma cells." (PMID 38698811, 2024). "For instance, phosphorylation of MCM3 by PLK1 was proved to participate in the proliferation and apoptosis of renal cell carcinoma cells." (PMID 33828075, 2021).
leukemia (3 papers, 2018 to 2022). A malignant (clonal) hematologic disorder, involving hematopoietic stem cells and characterized by the presence of primitive or atypical myeloid or lymphoid cells in the bone marrow and the blood. "It is noteworthy that phosphorylation of Ser611 of MCM3 has been identified by mass spectrometry in human leukaemia cells, but to date, no functional role has been assigned to this residue." (PMID 30069701, 2018).
squamous cell carcinoma (3 papers, 2015 to 2021). A carcinoma arising from squamous epithelial cells. "The purpose of this study was to evaluate the expression of MCM3 proteins and their diagnostic value in oral mucosal dysplasia and squamous cell carcinoma (SCC)." (PMID 26046103, 2015). "The expression of minichromosome maintenance-3 (MCM3) proteins and their diagnostic value in oral mucosal dysplasia and squamous cell carcinoma (SCC) is not well known." (PMID 26046103, 2015). "Studies showed an increased expression of MCM5 and a positive correlation with Ki-67, as well as an increased expression of MCM2, MCM3, and MCM7 in Larynx Epidermoid Carcinoma 2 (HEp-2) cell lines and positive correlations with Ki-67 in LSCC." (PMID 35053200, 2021).
brain tumors (2 papers, 2022 to 2023). "Considering the epigenetic disorders in pediatric brain tumors, we investigated the cause of MCM3 dysregulation at the methylation level." (PMID 36133906, 2022). "Considering the low mutation burden of pediatric brain tumors, we investigated the mechanism of MCM3 expression dysregulation." (PMID 36133906, 2022). "The results of this study demonstrated the dysregulation of MCM3 in most common cancers and showed its expression level in MB cell lines of pediatric brain tumors, which indicated its potential correlation with tumorigenesis." (PMID 36133906, 2022). "The RNA-seq data of different brain tumor cell lines from the Cancer Cell Line Encyclopedia (CCLE) showed the highest MCM3 mRNA expression level in MB." (PMID 36133906, 2022).
invasive ductal carcinoma (2 papers, 2021). "MCM3 is an independent risk factor for invasive ductal carcinoma." (PMID 33750478, 2021). "MCM3 were significantly up-regulated in invasive ductal carcinoma." (PMID 33552715, 2021).
leiomyosarcoma (2 papers, 2021 to 2023). An uncommon, aggressive malignant smooth muscle neoplasm, usually occurring in post-menopausal women. "Hence, MCM3 holds potential as a novel marker for uterine leiomyosarcoma." (PMID 38066476, 2023). "Using Barretina Sarcoma’s datasets, MCM3 was found to be overexpressed in pleomorphic liposarcoma (fold change = 2.316), myxoid/round cell liposarcoma (fold change = 2.769), myxofibrosarcoma (fold change = 2.122) and leiomyosarcoma (fold change = 2.212) when compared with normal samples." (PMID 34239894, 2021).
lung adenocarcinoma (2 papers, 2016 to 2025). A carcinoma that arises from the lung and is characterized by the presence of malignant glandular epithelial cells. "Our findings suggest thatDEGs encoding subunits of NADH, PRIM1, MCM3, MAPK1, STAT3, RAF1, and JAK1 might beassociated with the development of lung adenocarcinoma." (PMID 26840709, 2016).
lymph node metastasis (2 papers, 2022 to 2025). "However, MCM3 intensity did not exhibit significant differences in terms of histological grade or lymph node metastasis." (PMID 41502508, 2025).
metastatic disease (2 papers, 2015 to 2017). "In our study, Ki-67, MCM2 and MCM3 expression levels were higher in AC than in UA and SMA, which indicate aggressive, invasive, and metastatic neoplasm." (PMID 26823641, 2015).
neuroblastoma (2 papers, 2013 to 2025). Neuroblastoma (NB) is the most common solid, extracranial childhood tumor. "With this approach we identified four genes that are highly over expressed in high-risk neuroblastoma (CHAF1A, RRM2, MCM3, and MCM6) whose expression strongly correlates with poor outcomes." (PMID 24348903, 2013).
oral cancer (2 papers, 2022 to 2023). "Regarding future research, additional in vitro studies on human oral cancer cell lines would be needed to further confirm the association of MCM3 with oral cancer." (PMID 36611359, 2022). "Minichromosome maintenance 3 (MCM3) is a proliferative marker that has been investigated as a potential diagnostic biomarker in the diagnosis of oral cancer." (PMID 36611359, 2022). "Future evidence-based in vitro research may be done on cell lines of oral cancer and human oral cancer cell lines to further observe this type of association of MCM3 in OSCC cases." (PMID 36611359, 2022).
rectal adenocarcinoma (2 papers, 2020 to 2025). "In a TCGA dataset with the largest sample size (n=237) from the Oncomine database, MCM3 transcripts in the colon and rectal adenocarcinoma tissues were 1.668- and 1.660-fold higher than relevant normal tissues respectively." (PMID 32597491, 2020).
triple-negative breast carcinoma (2 papers, 2022 to 2025). An invasive breast carcinoma which is negative for expression of estrogen receptor (ER), progesterone receptor (PR), and human epidermal growth factor receptor 2 (HER2). "Overexpression of MCM2, MCM3, MCM4, and MCM6 is associated with luminal B, HER2+, and triple-negative breast cancers." (PMID 35401937, 2022).
viral infection (2 papers, 2017 to 2025). "The repression of MCM2, MCM3, MCM5, and MCM7 was associated with viral infection previously, but detailed functional studies have not been carried out." (PMID 28912786, 2017).
Alexander disease (1 paper, 2007). Alexander disease (AxD) is a rare neurodegenerative disorder of the astrocytes comprised of two clinical forms: AxD Type I and Type II manifesting with various degrees of macrocephaly, spasticity, ataxia and seizures and leading to psychomotor regression and death. "Other predictions include involvement of MCM2 and MCM3 in hypolactasia, S100B in Alexander disease, and CFHL1 in chronic hypocomplementemic nephropathy." (PMID 18042286, 2007).
anemia (1 paper, 2015). A reduction in the number of red blood cells, the amount of hemoglobin, and/or the volume of packed red blood cells. "In summary, Mcm3 downregulation during embryonic development caused RS in hematopoietic progenitors leading to fetal anemia; in adults, it reduced life expectancy and promoted lymphomagenesis." (PMID 26456157, 2015). "Mcm3-deficient erythroblasts display aberrant DNA replication patterns and fail to complete maturation, causing lethal anemia." (PMID 26456157, 2015). "Peripheral blood from Mcm3-deficient E14.5 embryos displayed a marked decrease in red blood cells (RBCs), haemoglobin concentration and hematocrit, all consistent with a phenotype of fetal anemia." (PMID 26456157, 2015).
asthma (1 paper, 2022). "We found MCM3 was lowly expressed in severe asthma, which indicated patients with severe asthma may suffered with the disorder of DNA replication and cell cycle." (PMID 35169275, 2022).
Bone tumors (1 paper, 2017). "Compared to ARCaPE tumors, ARCaPM and ARCaPM-Bone tumors displayed higher levels of MCM3 protein." (PMID 28424404, 2017).
breast tumors (1 paper, 2021). "Moreover, high expression of MCM3 in primary breast tumors is not only a strong and consistent prognostic marker, but also predictive of diminished response to tamoxifen therapy." (PMID 33398005, 2021).
cervical dysplasia (1 paper, 2023). "The MCM3 protein was significantly upregulated (p: 0.0053) in the cervical dysplasia group (≥LSIL) compared to the control (NILM) group." (PMID 37445651, 2023).
dysplasia (1 paper, 2015). A usually neoplastic transformation of the cell, associated with altered architectural tissue patterns. "In samples of dysplastic epithelium, MCM3 expression increased gradually and became stronger from mild dysplasia to severe dysplasia but did not have significant difference (p= 0.93)." (PMID 26046103, 2015).
fibrosarcoma (1 paper, 2021). A malignant mesenchymal fibroblastic neoplasm affecting the soft tissue and bone. "MCM3 was also overexpressed in fibrosarcoma with a fold change of 2.979 and synovial sarcoma with a fold change of 2.167, reported in Detwiller Sarcoma." (PMID 34239894, 2021).
gastric cancer (1 paper, 2023). A primary or metastatic malignant neoplasm involving the stomach. "E2F1 may be crucial in the development of gastric cancer by influencing the cell cycle pathway and modulating its target gene MCM3, which may interact with MCM4, MCM5, and MCM7." (PMID 37594635, 2023).
HCMV infection (1 paper, 2012). "On the basis that MCM3AP was initially suggested to be an MCM3 acetylation factor, we tested whether HCMV infection or over-expression of IE86 could lead to increased acetylation of MCM3." (PMID 23094019, 2012). "In contrast, although IE86 in isolation did not result in a decrease in MCM loading, HCMV infection did result in a decrease in loading of MCM3, as expected." (PMID 23094019, 2012).
kidney cancer (1 paper, 2015). Primary or metastatic malignant neoplasm involving the kidney. "The MCM3 gene was found to be overexpressed in various human cancers, including kidney cancer." (PMID 26283601, 2015). "From the unique set of genes detected by CANOVA, a few were reported to be relevant to kidney cancer/disease: FAH, MCM3 and UGT1A9." (PMID 26283601, 2015).
mastitis (1 paper, 2022). Inflammation of breast tissue during lactation or postpartum due to an obstructed duct or infection. "In this study, the increased gene expression of ORC1, ORC2, ORC4, MCM3, MCM5, and MCM6 in the neutrophils of cows with high SCCs indicated that the cell cycle may be activated in neutrophils in high mastitis risk cows during the transition period." (PMID 35572521, 2022).